IL6 (interleukin 6)
Diseases named in the same sentence as IL6 in open-access papers (continued):
Sharing a sentence is not in itself a finding about the gene and the disease.
Obesity (continued). "Another crossover intervention examining a low-calorie lacto-ovo-vegetarian diet showed a non-significant increase in IL-6 and TNF-α concentrations and WBC count compared to a low-calorie Mediterranean diet intervention in individuals with overweight or obesity." (PMID 36558530, 2022). "However, regarding the increase in IL-6, CRP, and TNF-α in adolescents with obesity, resistance training (RT) did not lead to significant differences." (PMID 36293806, 2022). "In addition, a meta-analysis confirms observations that IL-6 and TNF-α levels are related to obesity but not PCOS occurrence, whereas CRP levels are elevated in PCOS independent of obesity." (PMID 32934654, 2020). "Both obesity and O3I were significant predictors of CRP, but not for TNF-α or Il-6." (PMID 31892115, 2019). "Within the bone marrow, the levels of haematopoiesis-related IL-6 and TNF-α decreased after 4T1-cells injection in HFD-mice whereas increased in the controls, suggesting that upregulation of both cytokines, regardless of the tumor, is disrupted by obesity." (PMID 31616626, 2019). "Furthermore, levels of IL-6 and A-FABP were significantly higher in the diabetes with obesity group compared with those in the diabetes without obesity group (P < 0.05)." (PMID 27819006, 2016). "Obesity produces greater levels of systemic inflammatory factors, including adipose tissue macrophages, circulating lymphocytes, and pro-inflammatory cytokines (e.g., TNF-α, IL-6, TGF-β1, and C-reactive protein), than is produced in non-obese states." (PMID 27487262, 2016). "Four studies reported similar levels of IL-6 and five studies reported similar levels of adiponectin between obese and nonobese individuals with CP, whereas 3 studies reported comparable levels of GCF leptin among CP patients with and without obesity." (PMID 27795608, 2016). "Thus, in postmenopausal women with overweight/obesity, decreases in METRNL levels and increased IL-6 levels could be expected, which might explain the negative correlations observed between them." (PMID 40806137, 2025). "For that purpose, group of 45 children with obesity (OB) and group of 45 age‐matched children without obesity (CG) were examined in terms of serum levels of miR‐27a and biochemical parameters: fasting blood glucose, adiponectin, leptin, resistin, subfatin, visfatin, and TNF‐α, IL‐6." (PMID 34918493, 2022). "Hypoadiponectinemia in obesity may result from increased production of pro-inflammatory cytokines, such as tumour necrosis factor α (TNF-α) and interleukin 6 (IL-6), or from negative feedback of adipokine on its own production and the production of its receptors." (PMID 36556428, 2022). "Obesity-driven BRCA1 upregulation is not able to be explained by DNA methylation (EPIC array) or by short-term treatment of chorionic villous explants at 2.5% oxygen with tumor necrosis factor α (TNF-α) (50 mg/mL), leptin (100 mg/mL), interleukin 6 (IL-6) (100 mg/mL), or high glucose (25 nM)." (PMID 31940810, 2020). "Another recent publication reported that patients with metabolic diseases (obesity, type 2 diabetes, metabolic syndrome, cardiovascular disease, and nonalcoholic fatty liver disease) had a significant decrease in TNF-α plasma levels with CoQ10 supplementation but not CRP or IL-6." (PMID 31083534, 2019). "Interestingly, our data suggest that inflammation modulated by IL-1β, IL-6, PLAUR, and CCL2 in the VAT could be related to anxiety and mood disorders as long as patients are not in an obesity state." (PMID 30504920, 2018). "However, in agreement with our cumulative meta-analysis and previous standard meta-analyses, inclusion of patients using psychotropic medication and the lack of adjustment for overweight/obesity resulted in slightly larger effect size estimates between the levels of CRP, IL-6 and depression." (PMID 26065825, 2015).
Obesity (continued). "Inflammatory adipokines [IL-6, IL-10, ACE, TGFβ1, TNFα, IL-1β, PAI-1, and IL-8] plus one anti-inflammatory [IL-10] adipokine were identified whose circulating levels as well as in vitro release by fat are enhanced in obesity and are primarily released by the nonfat cells of human adipose tissue." (PMID 20508843, 2010). "Because the dietary model of NASH we used does not induce obesity or insulin resistance, i.e. important features of the human condition, future studies using different models of NASH should shed further light on the role of IL-6 in the development of steatohepatitis." (PMID 19936233, 2009). "Serum TNF-α, IL6, IL1β and MCP-1 levels have been identified upregulated in obese mice and modulated by adipocyte TRPM7 knockout in our study, indicating that adipocyte TRPM7 might be regulated by aberrant cytokines with coupled positive-plus-negative feedback circuits in response to obesity." (PMID 36717580, 2023).
Sepsis (3,140 papers, 2005 to 2026). Sepsis is defined as life-threatening organ dysfunction caused by a dysregulated host response to infection. "The role of IL-6 in sepsis and S-AKI is mainly associated with the intensity of immune cell infiltration and their interaction and activation in defense towards pathogens." (PMID 41614949, 2026). "Elevated IL6 levels are associated with an increased risk of severe sepsis and an increased death rate from severe sepsis." (PMID 41598258, 2026). "IL‐10 helps prevent hyperactivation of the innate immune system by inhibiting the effects of cytokines such as TNF‐α, IL‐1β, and IL‐6, thereby reducing the risk of multiple organ failure, and mitigating complications related to sepsis." (PMID 41573125, 2026). "Interleukin-6 is a pro-inflammatory cytokine which is a well-known diagnostic and prognostic marker of sepsis in people and dogs." (PMID 40512747, 2025). "This is especially relevant in immunosuppressed patients at risk for sepsis after IL‐6 inhibitors and high‐dose steroids." (PMID 40391237, 2025). "The concentration of IL-6 has been proposed as a potential diagnostic marker for sepsis and septic shock as well as a viable all-cause mortality predictor, with some case reports documenting an increase of up to 7500 times the normal level." (PMID 40497942, 2025). "A diagnostic model comprising 5 metabolicfeatures and IL-6 distinguished SINS from sepsis at clinical suspicion(AUC 0.79, sensitivity 0.85, specificity 0.82)." (PMID 40305123, 2025). "miR-223 negatively regulated the expression of STAT-3 and IL-6 in mouse hearts. loss of miR-223/-223* causes an aggravation of sepsis-induced inflammation, myocardial dysfunction and mortality." (PMID 40041174, 2025). "Mitochondrial dysfunction is a major mechanism of acute kidney injury (AKI), and increased circulating interleukin 6 (IL-6) is associated with systemic inflammation and death due to sepsis." (PMID 41355794, 2025). "Our study showed that IL-6 is a new biomarker with high sensitivity and good specificity for identifying sepsis, and it has been linked with a better diagnostic value than CRP." (PMID 40242671, 2025). "Organ dysfunction in sepsis is often associated with elevated levels of cytokines such as IL-1β, IL-6, and TNF-α and activation of nuclear factor kappa B (NF-κB) pathways." (PMID 40896042, 2025). "Its diagnostic value surpasses that of CRP, suggesting that IL-6 testing should be prioritized in clinical evaluations for suspected sepsis to improve early diagnosis and treatment strategies." (PMID 40242671, 2025). "While FnBPs exhibit negligible direct arthritogenicity, they drive interleukin-6 (IL-6)-dominated cytokine storms via integrin α5β1/fibronectin bridging, thereby inducing weight loss, increased mortality, and bacteremia in murine sepsis models." (PMID 41170422, 2025). "While IL-6 is a sensitive diagnostic biomarker for sepsis (85.0% sensitivity; and 62.0% specificity) and correlates with sepsis-related mortality, it lacks specificity for abdominal sepsis." (PMID 40510342, 2025). "Excessive activation of IL-6 is closely associated with immune dysfunction and kidney damage in sepsis." (PMID 40166075, 2025). "In patients with sepsis, the IL‐6/JAK/STAT3 pathway is highly up‐regulated and associated with muscle atrophy." (PMID 39435630, 2025). "Univariate analysis suggested that body temperature, respiratory rate, neutrophil count, PCT, and IL-6 emerged as significant risk factors for sepsis." (PMID 41567194, 2025). "The results of the PROWESS study showed that increased levels of IL-6 were a risk factor for AKI in patients with sepsis, emphasizing the role of inflammation in its development." (PMID 40142279, 2025). "In melanoma, the expansion of MDSCs driven by sepsis-induced IL-6 has been linked to accelerated tumor growth and reduced patient survival." (PMID 40563999, 2025).
Sepsis (continued). "Here, the risks of death and complications were not firmly associated with specific cytokines, except the association of IL-6 with sepsis in the multivariate regression analysis." (PMID 40732663, 2025). "Decreased IL‐6 levels were negatively correlated with susceptibility to sepsis (OR, 0.7; 95% CI, 0.55–0.88; p = 0.002)." (PMID 40501500, 2025). "In neonates at risk of vertical transmission, elevated cord blood IL-6 has shown excellent sensitivity and specificity for early-onset sepsis, though its positive predictive value increases significantly only when combined with other ILs." (PMID 41300951, 2025). "The GG genotype boosts IL-6 production over the CC, potentially intensifying inflammation and mortality risk in sepsis." (PMID 40149943, 2025). "A decreasing trend in IL-6 values in patients during sepsis follow-up is thought to be associated with a better prognosis in sepsis." (PMID 39955435, 2025). "Our previous studies found that IL-27 levels are elevated in sepsis-associated AHI in humans and in a mouse model of sepsis and that IL-27 plays a role in promoting macrophage M1 polarization and increasing IL-6 and TNF-α levels." (PMID 40046257, 2025). "UC IL-6 has shown consistent associations with early neonatal outcomes, including sepsis, respiratory distress and HIE, underscoring its potential as an early warning biomarker." (PMID 41302151, 2025). "Other genetic studies have shown that higher levels of IL-6 are predicted to causally increase the odds of sepsis and sepsis-related death, as well as incur an increased risk of tuberculosis infection; conversely, they are likely to be protective in pneumonia." (PMID 40819633, 2025). "Sepsis cases (median IL-6 = 326 pg/mL) differed significantly from low-risk episodes (median 21 pg/mL; p < 0.01)." (PMID 40647525, 2025). "ROC analysis demonstrated the diagnostic efficacy of IL-6 in differentiating HDs from patients with sepsis, yielding an AUC of 0.972." (PMID 40230851, 2025). "Procalcitonin demonstrated superior diagnostic accuracy compared with C-reactive protein and interleukin-6 for the early detection of postoperative sepsis following lung decortication." (PMID 41281040, 2025). "High levels of IL-6 in cord blood and low peripheral neutrophil counts on the first day of life are associated with an increased risk of late-onset sepsis in preterm infants." (PMID 40640885, 2025). "IL-6 is a potential prognostic and diagnostic marker for sepsis, and it is necessary to evaluate its levels in patients with sepsis or suspected sepsis." (PMID 39955435, 2025). "In sepsis, IL-6 has been studied extensively, with multiple investigations demonstrating associations between IL-6 concentrations, disease severity, and adverse outcomes." (PMID 41155261, 2025). "Building upon the established diagnostic utility of IL-6 in sepsis, the primary focus of this study shifts towards elucidating its prognostic value." (PMID 40149943, 2025). "Additional interleukins implicated in the proinflammatory response during sepsis include IL-6, IL-12, and IL-17, which play critical roles in immune cell activation and cytokine induction." (PMID 41268545, 2025). "PCT (Procalcitonin level), WBC (white blood cell count), and IL-6 (interleukin-6 level) were the characteristics most strongly associated with sepsis risk." (PMID 41088618, 2025). "Previous studies have shown that IL-6 and IL-8 are associated with sepsis in children and newborns and are closely related to sepsis severity." (PMID 39886481, 2025). "It was necessary to examine serum IL-6 levels at narrow time intervals during the sepsis process and investigate the changes in the outcomes of systemic inflammation caused by IL-6 on organ injury over time to understand IL-6’s behavior in sepsis." (PMID 39955435, 2025). "Low interleukin-6 (IL-6) and high interleukin-10 (IL-10) levels are associated with improved outcomes in sepsis." (PMID 41158471, 2025).
Sepsis (continued). "A detailed analysis of patients' demographic and clinical profiles revealed statistically significant differences between deceased and discharged patients regarding the presence of underlying oncologic pathology, sepsis status, and levels of IL-6 and CRP." (PMID 41011807, 2025). "Focused on the interactions of sepsis and IL-6 related pathways, some chronic diseases have been studied for association with sepsis, containing insulin resistance, Alcoholic liver disease (ALD), Alzheimer disease (AD), and atherosclerosis." (PMID 39891057, 2025). "In this trial, patients were stratified according to levels of interleukin-6 (IL-6), a marker associated with worse outcomes in sepsis." (PMID 41157190, 2025). "Myocardial dysfunction involves inflammatory mediators such as TNF-α and IL-6, while sepsis-associated acute kidney injury (SA-AKI) arises from hypoperfusion and inflammation, heightening the risk of progression to chronic kidney disease." (PMID 40265185, 2025). "Elevated levels of IL-6 have been linked to poor outcomes in sepsis patients, reinforcing the potential of targeting these pathways for therapeutic intervention." (PMID 41041634, 2025). "Using a cecal ligature and puncture (CLP)-induced sepsis model, we assessed IL-6 levels, weight loss, myofiber cross-sectional area, resting membrane potential, and connexin expression in control and Cx43/Cx45-deficient mice." (PMID 40066286, 2025). "One preliminary experience in adults suggested that the use of the IL-6 receptor antibody tocilizumab is beneficial in patients with hematological malignancy who suffer from elevated IL-6 levels caused by severe sepsis." (PMID 40136690, 2025). "A previous study reported that among the various cytokines, IL-6 was the most valuable cytokine associated with sepsis severity and outcome prediction." (PMID 40136690, 2025). "In a separate analysis of two studies reporting log-transformed odds ratios (284 patients), a significant association was found between elevated IL-6 levels and mortality in sepsis patients." (PMID 40149943, 2025). "Elevated IL-6 levels often precede other clinical signs and are associated with the severity of sepsis and mortality risk." (PMID 40310334, 2025). "It has also been reported that T cell– and IFN-γ–deficient mice showed apparently reduced serum IL-6 levels and markedly resist E. coli infection or sepsis, indicating that IFN-γ–producing T cells play a vital role in bacterial sepsis." (PMID 40510337, 2025). "In sepsis, IL-6 is strongly associated with thrombocytopenia and is a marker of poor prognosis, with complications including dysregulated haemostasis and organ dysfunction." (PMID 40497942, 2025). "Studies assessing the diagnostic performance of IL-6 in late-onset neonatal sepsis, defined as sepsis occurring after 72 h of life, were considered for inclusion." (PMID 40892314, 2025). "Elevated IL-6 levels, a hallmark of sepsis, correlate with disease severity and act as diagnostic and prognostic markers." (PMID 40003683, 2025). "IL-6 serves as a valuable biomarker of both diagnostic and prognostic significance for sepsis and septic shock." (PMID 39955435, 2025). "Collectively, these findings indicate that ACSL4, GPX4, and PTGS2, along with IL-6, hold significant diagnostic and prognostic value in sepsis." (PMID 40264754, 2025). "While elevated IL-6 levels are clearly associated with the presence and severity of sepsis, a more nuanced understanding of their relationship with patient outcomes is needed." (PMID 40149943, 2025). "CRP is a well-established biomarker for sepsis, while IL-6, a proinflammatory factor, is strongly associated with disease severity and mortality in sepsis." (PMID 40568710, 2025). "Circulating levels of IL-6 are commonly elevated in neutropenic patients with sepsis, as we observed in our experiment, and are associated with more severe outcomes." (PMID 40534875, 2025).